BCL2 (BCL2 apoptosis regulator)
Diseases named in the same sentence as BCL2 in open-access papers (continued):
Sharing a sentence is not in itself a finding about the gene and the disease.
cancer (continued). "In cancer cells, pro-apoptotic factors (such as Bim) are often upregulated, establishing a dependency on anti-apoptotic Bcl-2 to prevent apoptosis." (PMID 30718472, 2019). "The mitochondrial apoptotic pathway has been manipulated for cancer treatment such as with the discovery of the Bcl-2 inhibitor ABT-737, which has been extensively tested." (PMID 31067776, 2019). "Due to their pivotal role as inhibitors of apoptosis, pro-survival Bcl-2 proteins have been considered promising targets for anti-cancer therapy." (PMID 31825969, 2019). "Recently, a number of compounds have been demonstrated to inhibit anti-apoptotic Bcl-2 proteins, and some of them have entered clinical trials as potential cancer treatments." (PMID 31057406, 2019). "Using The Cancer Genome Atlas (TCGA) data set, we found weak positive correlation between PRDM10 and Bcl-2 in several cancer types including cancers of the breast, colon, and lung tissues." (PMID 31143550, 2019). "Although these two pharmacological agents were shown to be effective at killing several Bcl‐2‐dependent cancer types, they were also found to induce thrombocytopenia and deregulate Ca2+ homeostasis in platelets, effects attributed to Bcl‐xL inhibition." (PMID 30266036, 2019). "In the present study, we found that ERβ promoted Bcl-2 expression and reduced cancer cell apoptosis." (PMID 31076571, 2019). "Autocrine production of IL-33 has been suggested to contribute to human cancer cell survival, migration and resistance to chemotherapy, through the up-regulation of anti-apoptotic proteins including Bcl-2, and via ST2/STAT3." (PMID 31535033, 2019). "Cancer cells avoid apoptosis through various strategies that include increased expression of pro-survival proteins such as BCL-2, BCL-XL, or MCL-1." (PMID 31399555, 2019). "The ratio of Bcl-2 and Bax affects the relative sensitivity or resistance of cancer cells to apoptotic stimuli and therapeutic drugs." (PMID 32047442, 2019). "Accumulating studies indicate that TW-37 displays anti-proliferative or pro-apoptotic properties in various types of cancers by inhibiting Bcl-2 and/or Mcl-1 in vitro and in vivo." (PMID 31052354, 2019). "Sensitization of cancer cells to anti-cancer drug-induced apoptosis is related with down-regulation of apoptosis related proteins (Mcl-1 or Bcl-2) and inhibition of phosphorylation of STAT3." (PMID 31817696, 2019). "In the current study, Bcl-2 marker was targeted for immunohistochemical analysis for its role in cancer prognosis." (PMID 31754362, 2019). "The expression pattern of Bax and Bcl-2 not only differs between various cancer, but even within the same cancer." (PMID 31861952, 2019). "Cancer cells have long been known to evade cell death through overexpression of anti-apoptotic BCL-2 members or through down-regulation of BH3-only proteins." (PMID 31692812, 2019). "In the past few decades, this protein has been demonstrated to have high efficacy in cancer therapy, and several approaches targeting Bcl-2 have been tested clinically (e.g., oblimersen, ABT-737, ABT-263, obatoclax mesylate, and AT-101)." (PMID 31662966, 2019). "Increased expression of anti-apoptotic Bcl-2 or decreased expression of pro-apoptotic Bax confers resistance of tumor cells to apoptosis in many cancers." (PMID 30446901, 2019). "Synthetic peptides based on VDAC1 binding sites were used to inhibit Bcl2, Bcl-xL, and HKII, preventing their association with VDAC1 and thus inhibiting cancer cells’ ability to evade apoptosis." (PMID 31261935, 2019). "The analysis of the gene expression revealed that both compounds inhibited the proliferation in all cells (H3) and activated of mitochondrial events of apoptosis (BAX/BCL-2) in two cancer cell lines (SNB-19 and MDA-MB-231)." (PMID 31307242, 2019). "LncRNA PANDAR acts as a cancer suppressor gene by regulating Bcl-2 to affect cell apoptosis in NSCLC." (PMID 31558162, 2019).
cancer (continued). "At 2 years post-diagnosis, 73% of cats with a Bcl-2–negative FMC had died from cancer, compared to 51% of cats with a Bcl-2–positive FMC." (PMID 30630524, 2019). "For ABT‐199, we validated that the concentrations/time periods used were capable of inducing cell death in Bcl‐2‐dependent cancers." (PMID 30266036, 2019). "Cancer cells expressing high Bcl-2 levels are sensitive to ABT-737 treatment, and ABT-737 combines with cytotoxic drugs against solid tumors and hematological malignancy and overcome cancer cell resistance." (PMID 31906234, 2019). "Does anti-apoptotic Bcl-2 protein overexpression make cancer cells more resistant to apoptosis than healthy cells?" (PMID 31681471, 2019). "It has emerged that the sensitivity of a cancer cell to BCL-2 inhibition depends, at least in part, due to the quantity of pro-apoptotic proteins that are bound by the BCL-2 molecule." (PMID 31717784, 2019). "CircAMOTL1 overexpression in cancer cells remarkably increased anti-apoptotic gene BCL2 expression and inhibited pro-apoptotic gene BAX and BAK expression." (PMID 31819016, 2019). "Compounds such as Gossypol, Navitoclax, ABT-737 and α-TOS act as mimetics of the Bcl-2 homology-3 domains to kill cancer cells through the activation of post-mitochondrial apoptotic signaling." (PMID 31653274, 2019). "Cells with overexpression of anti-apoptotic proteins in the Bcl-2 family such as Bcl-2, Bcl-XL, and Mcl-1 in cancer cells are considered to be “less primed” to apoptosis and are associated with poor prognosis." (PMID 31092272, 2019). "In contrast to our observations, Bex1 has been shown to have a pro-apoptotic role by binding to Bcl2 in cancer cells." (PMID 31827131, 2019). "MiR-7 targets and downregulates oncogenic factors in cancer-associated signaling pathways including EGF, Bcl-2, Raf1, and Akt/PI3K61." (PMID 30783079, 2019). "Molecular docking mechanism of GA was performed through binding simulation analysis for various cancer signaling pathway, viz., Bcl-2, Pl3K, NF-κB, Akt/PKB, and Stat-3." (PMID 31357897, 2019). "QC and QS also promoted the apoptosis of primary cancer hepatocytes by upregulating caspase-3 and downregulating BCL-2 expression." (PMID 30723284, 2019). "The increase in Bcl-2 levels in cancer cells blocks the release of cytochrome C from the mitochondria." (PMID 31835393, 2019). "According to current data, approximately 19 different Bcl-2 inhibitors are the subjects of preclinical or clinical studies and various combinations of therapeutic methods are being assessed for Bcl-2-positive cancer." (PMID 31662966, 2019). "In apoptotic pathway, caspase-3 plays a crucial role in the activation of apoptosis by cleaving various key cellular proteins including Bcl-2, which normally prevents apoptosis in cancer cells." (PMID 31652886, 2019). "STAT3 transcriptionally regulates expression of a set of downstream genes including c-Myc and Bcl2 in control of tumorigenesis and chemo-resistance in cancer." (PMID 32010177, 2019). "AM can regulate the apoptosis of cancer cells by upregulating the apoptosis-related proteins caspase 3 and caspase 9 and increasing the proportion of Bax/Bcl-2." (PMID 31636686, 2019). "Our in-silico and in vitro investigation revealed that EPU-0001 effectively target BCL-2 protein to induce apoptosis in cancer cells." (PMID 31450709, 2019). "BH3 mimetics have been developed in order to counteract the Bcl‐2‐dependent evasion of apoptosis, common in cancers." (PMID 30266036, 2019).
cancer (continued). "The more detailed mechanistic study demonstrated that compound 8l inhibited the proliferation of MDA-MB-231 cancer cells by inducing apoptosis by downregulating Bcl-2 and upregulating Bax protein levels." (PMID 30915869, 2019). "In cancer cells, this is achieved by altered expression levels of either the pro‐ or anti‐apoptotic B‐cell lymphoma 2 (Bcl‐2) family members, predominantly located at the mitochondrial membranes." (PMID 30266036, 2019). "The development and use of drugs which target the pro-survival members of the Bcl-2 family such as Bcl-2 and Bcl-xL is becoming an increasingly common strategy to combat intrinsic resistance to first line chemotherapy in multiple cancer types." (PMID 30875757, 2019). "Bcl‐2 antagonism through Bcl‐2 homology 3 (BH3) mimetics has emerged as a novel anti‐cancer therapy." (PMID 30266036, 2019). "In similar lines, C5 methylation within the G-rich promoter region of the B-cell lymophoma (BCL-2) gene, which forms G4 structure, was observed to lead to repression of BCL-2 known to be abnormally overexpressed in many cancers." (PMID 30736345, 2019). "ABT-199 is a small molecule inhibitor that selectively binds to Bcl2 and currently is being used in clinical trials for cancer treatment." (PMID 31608069, 2019). "For example, the selective anti-cancer activity of venetoclax, an inhibitor of the anti-apoptotic protein BCL-2, has finally validated the clinical utility of directly targeting tumor cell death." (PMID 31727958, 2019). "Comprehensive studies into the abundance, modifications, and interactome of each of the pro-survival Bcl-2 members for each cancer type would generate important knowledge, useful for optimization and design of BH3-mimetics." (PMID 31825969, 2019). "The Bcl-2 protein promotes the survival of cancer cells by inhibiting apoptosis, and it also induces resistance to chemotherapy." (PMID 31892356, 2019). "Our results suggest the overexpression of Akt1 and 2 with respect to migration and expression of Bcl-2, cyclin D1, and survivin proteins, which are important for cancer cell survival and proliferation." (PMID 31252679, 2019). "Auraptene, in the present study, triggered apoptosis in cancer cells at concentrations of 100 and 400μg/ml, by increasing Bax/Bcl-2 ratio." (PMID 31309072, 2019). "Bcl-2 protein is involved in cell apoptosis and is considered an interesting target for anti-cancer therapy." (PMID 30781512, 2019). "It is accepted that BFL1 prevents apoptosis under specific physiological settings, and that BFL1 contributes to tumour progression and drug resistance in selected types of human cancer, akin to BCL2, BCLXL and MCL1." (PMID 30560933, 2019). "It was determined that Yoda1 sensitizes cancer cells to TRAIL via calpains by cleaving Bcl-2 and truncating Bid." (PMID 31685811, 2019). "We further demonstrated that SSd exerted its anti-carcinogenic effect in these cancer cell lines by decreasing the antiapoptotic protein Bcl-2 and increasing the pro-apoptotic protein Bad." (PMID 31191326, 2019). "It is proposed that cancer cells, in which the mitochondria contain high levels of Bcl-2 and Bim, are most sensitive to toxic stimuli, including chemotherapeutic drugs." (PMID 30884858, 2019). "Since RRM2 regulates BCL-2 in various types of cancers and plays an active role in tumor progression, it can serve as a potential target for cancer therapy." (PMID 31064156, 2019). "In the past decade, several potent small molecule as BCL-2 inhibitors have been developed which demonstrated effective anti-cancer activity in vitro as well as in vivo." (PMID 31450709, 2019). "Nevertheless, it has been shown that BH3 binding and the amount of Bim scaffolded by anti-apoptotic Bcl-2 proteins can be used as a predictive marker for the apoptotic response of cancer cells to chemotherapy." (PMID 30884858, 2019). "Upregulation of pro-survival BCL-2 proteins is a known mechanism by which cancer cells disrupt apoptosis signaling." (PMID 30728900, 2019).
cancer (continued). "Bcl2 is an oncogene that promotes survival and regulates pro- and anti-apoptotic pathways, which is one of the hallmarks of cancer." (PMID 31652963, 2019). "Another drug targeting Bcl-2 is geneta (G-3139), which modulates apoptosis in several cancers such as melanoma and lymphoma." (PMID 31652965, 2019). "In cancer, a decrease of mitochondria CL was found to be accompanied by a decrease in the expression of cytochrome c, and an increase of the ratio Bax/Bcl-2, and was correlated to OXPHOS dysfunction and consequently to muscle catabolism associated with cancer." (PMID 31530825, 2019). "Bcl-2 overexpression enables cancer cell survival despite pro-apoptotic challenges related to oncogenic stress such as genomic aberrations." (PMID 30718472, 2019). "We then tested for differences in BCL2 expression levels in the RNA-seq data of 1417 pan-cancer samples from TCGA." (PMID 31044156, 2019). "These molecules trigger apoptosis in cancer cells that are primed to death due to high levels of Bax or Bim, and thus are addicted to Bcl-2 for their survival." (PMID 29899382, 2019). "One such route frequently utilized by cancer cells is upregulation of the antiapoptotic BCL2 family proteins, including BCL2, MCL1, BCL2A1, and BCLxL." (PMID 30635584, 2019). "In this study, we report that TMPRSS4 upregulates bcl-2 and survivin to enhance cancer cell survival, and inhibits anoikis and drug treatment sensitivity, potentially via upregulation of AP-1, Sp1, and NF-κB." (PMID 31292507, 2019). "S. parasitica downregulate expression of CyclinD1, Bcl-2, and Ki-67 protein, and upregulate the expression of Bax protein which helps in the inhibition of cancer cell line and apoptosis of cancer cell in vivo." (PMID 31892257, 2019). "The mechanism by which autophagy is induced has been widely reported, and inhibition of the AKT/mTOR, ROS/AMPK, and Bcl-2/Beclin-1 signaling pathways are known to induce autophagy in cancer cells." (PMID 30627053, 2019). "Recent studies have validated that ECRG4 induces apoptosis in several cancers through the regulation of Bax and Bcl-2, and through the activation of caspase-3, which cleaves PARP protein." (PMID 30918105, 2019). "It has been demonstrated that imbalance of Bcl-2 and Bax can induce the ΔΨm change and apoptosis of cancer cells." (PMID 31242894, 2019). "We and others have shown that treatment of drug naïve cells with BET inhibitors results in the potent and rapid repression of a set of broadly expressed genes such as Myc, Bcl2 and Cdk6 that are essential for the survival of cancer cells 31–34." (PMID 31222014, 2019). "In cancer cells, it has been observed that Pin1 enhances conformational stabilization and cell death resistance capability of BCL2, an anti-apoptotic effector that in turn inhibits apoptosis via inactivation of BAX." (PMID 31614723, 2019). "One of the mechanisms of drug resistance in cancer is the modification of the genes and proteins controlling the mitochondrial pathway of apoptosis, such as members of the B-cell lymphoma 2 (Bcl-2) family." (PMID 31798573, 2019). "Some synthetic analogues of the marine natural compound jahanyne, isolated from Lyngbya sp., were shown to induce apoptosis in cancer cells by binding Bcl-2." (PMID 30678065, 2019). "Targeting anti-apoptotic BCL2 family proteins has become an attractive therapeutic strategy for many cancers, and the BCL2-selective inhibitor ABT-199 (venetoclax) has obtained clinical success." (PMID 30796196, 2019). "As the BCL-X and BCL-2 families have essential roles in apoptotic regulation and were initially discovered in the cancer setting, they have garnered interest as therapeutic targets." (PMID 30792387, 2019). "Nevertheless, the development of BH3 mimetics continued, resulting in ABT‐737 and its orally available successor ABT‐263 (navitoclax), as selective on‐target inhibitors of Bcl‐2, Bcl‐xL and Bcl‐w that are able to induce cancer cell death." (PMID 30266036, 2019).
cancer (continued). "The results also showed that Tan I‐induced increased expression of the proapoptotic gene Bax and decreased expression of the anti‐apoptotic gene Bcl‐2 is the possible mechanism of its anti‐cancer effects." (PMID 31293090, 2019). "Together, these results suggest that TMPRSS4 promotes cancer cell survival and drug resistance, potentially through upregulation of bcl-2 and survivin." (PMID 31292507, 2019). "We notice that, despite the classification of Bcl-2 members as either inhibitor or executioner of apoptosis, their regulation in cancers is far from black and white, and the regulation is to a high degree tissue-context-dependent." (PMID 31825969, 2019). "Considering these facts, we have hybridized carbazole and piperazine pharmacophore using ethyl urea linker to discover potent BCL-2 targeting anti-cancer agent ECPU-0001." (PMID 31450709, 2019). "Actually, there are such previous studies showing that BH3 mimetics had drug resistances by compensatory activity of Mcl-1 for the inhibition of Bcl-2/Bcl-xL and Mcl-1 activation sensitized cancer cells to BH3 mimetics." (PMID 32257914, 2019). "For example, BIRC5 (also known as Survivin) and BCL2 are anti-apoptotic genes that promote cancer cell survival, whereas IL17A, IL23 and IL6 play important roles in promoting pro-inflammatory oncogenic signaling." (PMID 31292446, 2019). "Our previous studies have shown that CDKI‐73 induced apoptosis by targeting short‐lived pro‐survival mRNA, such as Mcl‐1, XIAP and Bcl‐2 in cancer cells." (PMID 31398271, 2019). "In order to target the interaction between pro- and anti-apoptotic BCL2 proteins in cancer, a new class of compounds, the BH3-mimetics, has been developed." (PMID 30941349, 2019). "Venetoclax, currently approved for use in patients with chronic lymphocytic leukemia, navitoclax, TW-37, GX15-070 and BM-1197, are Bcl-2 or Bcl-xL inhibitors with anticancer activity in a broad range of cancer types." (PMID 31653274, 2019). "An imbalance between apoptosis-related proteins, such as Bcl-2 and Bax, can induce dysregulation of apoptosis, which can lead to onco-genesis and cancer progression." (PMID 31768130, 2019). "Despite being beneficial for injured tissue, the antiapoptotic functions of Bcl-2 proteins can instead be problematic in cancer, where cell proliferation is unchecked by apoptosis." (PMID 31227712, 2019). "Impact of pyridine 5l on the expression levels of Bax and Bcl-2 in HCT-116 cancer cells treated with the compound at its IC50 concentration." (PMID 30722708, 2019). "The suppression of the STAT3 signaling pathway, which targets both CCND1 and Bcl-2, led to down-regulation of the expression of both proteins, thereby inducing cellular apoptosis in cancer cells." (PMID 31718693, 2019). "Contrary to protecting cancer cells from drug induced cell cycle arrest, Bcl2 can prolong their survival during this period; hence, proliferation resumes upon withdrawal of the drug." (PMID 31205469, 2019). "A number of small molecule inhibitors were previously designed to induce apoptosis against cancers by targeting anti-apoptotic Bcl-2 proteins characterized into groups based on their structure and function." (PMID 32257914, 2019). "In conclusion, hsa-miR-181a-5p and BCL2 are expected to be distinctive biomarkers of benign or malignant tumors and potential therapeutic targets of PTC." (PMID 31842912, 2019).